TMEM82 (transmembrane protein 82)
Tractability: Antibody: UniProt predicts a signal peptide or a membrane-spanning region.
Gene: Protein-coding gene on chromosome 1 (15,742,499 to 15,747,982, forward strand). Ensembl gene ENSG00000162460.
Subcellular location: Membrane
Subcellular location (Human Protein Atlas): Nucleoplasm; Cytosol
Gene Ontology:
Cellular component: membrane
Genetic constraint (gnomAD): Loss-of-function variants: 31 observed, 25.77 expected, observed/expected ratio (o/e) 1.2, 90% interval 0.9 to 1.62. The upper end of that interval is the gene's LOEUF score, 1.62, which puts it in group 6 of 6, group 1 being the genes least tolerant of losing a copy. Missense variants: 442 observed, 409.59 expected, observed/expected ratio (o/e) 1.08, 90% interval 1 to 1.17. Synonymous variants: 221 observed, 199.01 expected, observed/expected ratio (o/e) 1.11, 90% interval 0.99 to 1.24.
Homologues: Orthologues: chimpanzee TMEM82 (99% identical), macaque TMEM82 (89% identical), pig TMEM82 (85% identical), guinea pig TMEM82 (81% identical), rabbit TMEM82 (81% identical), dog TMEM82 (80% identical), mouse Tmem82 (80% identical), tropical clawed frog tmem82 (52% identical), zebrafish tmem82 (43% identical).
Diseases named in the same sentence as TMEM82 in open-access papers:
TMEM82 is named in the same sentence as 2 diseases in open-access papers, as found by Europe PMC text mining. Sharing a sentence is not in itself a finding about the gene and the disease. The quoted sentences say what the papers report.
cancer (1 paper, 2019). A tumor composed of atypical neoplastic, often pleomorphic cells that invade other tissues. "However, the rest of the genes (LGI1, PCSK2, CTNND2, SLC6A19, DAO, TMEM82 and CPNE7) could be related to CRC and have been previously identified in other types of cancer." (PMID 30940089, 2019).
TMEM82 also shares sentences with these, for which no sentence is quoted: colorectal cancer (1 paper).